CDK4 (cyclin dependent kinase 4)
Diseases named in the same sentence as CDK4 in open-access papers (continued):
Sharing a sentence is not in itself a finding about the gene and the disease.
breast cancer (continued). "The aim is to compare the efficacy and adverse events of different CDK4/6 inhibitors in breast cancer, and weigh the advantages and disadvantages, in order to provide more clinical drug reference for readers." (PMID 40104496, 2025). "Further, based on clinicaltrials.gov, the INAVO123 study is planned to evaluate inavolisib combined with letrozole and a CDK4/6 inhibitor in endocrine-sensitive breast cancer (NCT06790693)." (PMID 40711480, 2025). "Cyclin-dependent kinase 4 and 6 (CDK4/6) inhibitors radically changed the treatment paradigm for breast cancer." (PMID 41200193, 2025). "In the VERITAC‐2 pivotal Phase III clinical trial (NCT05654623), the study enrolled 624 patients with ER+/HER2− advanced breast cancer previously treated with CDK4/6 inhibitors and endocrine therapy, with primary endpoint of PFS." (PMID 41049269, 2025). "Cyclin-dependent kinase 4/6 inhibitors (CDK4/6i) represent a major advancement in the treatment of this subtype of breast cancer." (PMID 40244189, 2025). "CDK4/6 inhibitors in combination with endocrine therapy are now used as front-line treatment for patients with estrogen-receptor positive (ER+) breast cancer." (PMID 40826108, 2025). "Despite their known efficacy, most patients with advanced breast cancer develop resistance to CDK4/6i within 12–24 months of initiating therapy." (PMID 40940886, 2025). "ADELA (NCT06382948) is a phase III trial, where elacestrant combined with everolimus is compared to elacestrant alone in the ER+/HER2− advanced breast cancer population with ESR1-mutated tumors that have progressed on ET and CDK4/6i." (PMID 40244377, 2025). "In the six studies cited above regarding patients with HER2− breast cancer, CDK4/6 inhibitors, specifically abemaciclib, and talazoparib, a PARP inhibitor, were shown to be cost-effective." (PMID 41008856, 2025). "In 212 HR-positive advanced breast cancer patients treated with CDK4/6, the median follow-up time was 20 months." (PMID 41346024, 2025). "Combining endocrine therapy with CDK4/6 inhibitors has improved metastatic ER+ breast cancer disease control, significantly extending progression-free and overall survival." (PMID 40341770, 2025). "The integration of CDK4/6 inhibitors into early breast cancer care has raised questions about the extent of axillary staging needed for eligibility." (PMID 41514640, 2025). "The standard of care for HR+/HER2− breast cancer is a drug regimen consisting of endocrine therapy combined with a cyclin-dependent kinase 4/6 inhibitor (CDK4/6i)." (PMID 41155694, 2025). "Early studies have explored the efficacy of CDK4/6 inhibitors beyond breast cancer, extending into other solid and hematological malignancies." (PMID 39800748, 2025). "CDK4/6i serve as the first-line therapeutic agents for patients with HR+/HER2− breast cancer, exerting their therapeutic effects through cell cycle arrest, immune and metabolic regulation." (PMID 41219968, 2025). "AC682 is a chimeric compound that, given alone or plus CDK4/6is or PI3K/mTOR pathway inhibitors, showed anticancer activity in experimental ER+ breast cancer models, including those with ESR1 mutations." (PMID 40244377, 2025). "Palbociclib, a pioneering CDK4/6 inhibitor, has garnered approval for clinical use within China, marking a significant milestone in treating breast cancer." (PMID 40703553, 2025). "Materials and Methods: A retrospective multicenter analysis included 464 breast cancer patients treated with CDK4/6 inhibitors between January 2017 and April 2024." (PMID 40142360, 2025). "Previous evidence indicated that abemaciclib displays the highest potency in inhibiting CDK4 among the current recommended CDK4/6 inhibitors for advanced breast cancer." (PMID 40740245, 2025). "This study included 212 HR-positive advanced breast cancer patients who received CDK4/6 therapy at our department." (PMID 41346024, 2025).
breast cancer (continued). "This study has led to ongoing clinical trials using hydroxychloroquine and CDK4/6i to prevent relapse in breast cancer, with promising early findings." (PMID 41091336, 2025). "For example, the discovery and development of selective CDK4/6 inhibitors, such as palbociclib, ribociclib, and abemaciclib, have resulted in altered management of estrogen receptor–positive breast cancer." (PMID 40062557, 2025). "Based on the insights into B7-H4 degradation via lysosomes, we find that abemaciclib, an FDA-approved CDK4/6 inhibitor for breast cancer, reduces B7-H4 protein levels by enhancing lysosome biogenesis and abundance." (PMID 40341398, 2025). "In Romania, reimbursed standard treatment for HR-positive HER2-negative advanced breast cancer tumors is aligned with European Guidelines, which recommends a preferred first-line as CDK4/6 inhibitor plus ET." (PMID 39860516, 2025). "There are clinical trials in breast cancer testing hormone therapy combined with CDK4/6 inhibitors and mTOR inhibitors (ex." (PMID 40282469, 2025). "Most recently, RNA binding protein PRMT5 has been identified as a CDK4/6i resistance driver in breast cancer via controlling intron retention of cell cycle-regulating genes." (PMID 39667501, 2025). "CDK4/6 inhibitors are cornerstone therapies for advanced HR+/HER2- breast cancer, yet treatment response heterogeneity remains a major clinical challenge." (PMID 40746611, 2025). "Glycolysis-related glucose transporters and key enzymes are activated in breast cancer cells resistant to CDK4/6 inhibitors, promoting the glycolytic process." (PMID 40303296, 2025). "The primary aim of this study was to evaluate the impact of BMI on the efficacy of CDK4/6 inhibitors in patients with metastatic HR-positive breast cancer." (PMID 41346024, 2025). "Researchers have created a simple and universal nanoparticle platform loaded with palbociclib, which served as an effective inducer of ICD in breast cancer mice models receiving immunotherapy and avoided the adverse reactions of systemic use of CDK4/6is." (PMID 41463246, 2025). "This study supports the early use of CDK4/6 inhibitors combined with endocrine therapy as a cost-effective strategy for advanced HR+/HER2- breast cancer in China." (PMID 41383485, 2025). "Clinical trials have shown that abemaciclib, a CDK4/6 inhibitor, has anti-tumor activity in breast cancer, lung cancer, and other solid tumors." (PMID 39859343, 2025). "In summary, CDK4/6i have fundamentally transformed the therapeutic landscape of ER+ breast cancer, yet their broad application is constrained by heterogeneous benefit, cost, and toxicity, underscoring the need for proper patient selection." (PMID 41226361, 2025). "Given that tumor growth often relies on uncontrolled cell cycle progression, the cyclin D1/CDK4/6 axis has emerged as a key target for cancer therapy, including breast cancer." (PMID 40244377, 2025). "In breast cancer, estrogen receptor signaling upregulates the CDK4/6 pathway, leading to progression of the cell from the G1 to S phase and contributing to tumor growth." (PMID 40075623, 2025). "The clinical success of these drugs for the treatment of breast cancer has encouraged diverse clinical trials aimed at exploring novel combinatorial regimens of CDK4/6 inhibitors in different types of tumours." (PMID 41388212, 2025). "These patient preferences are important for shared decision making when discussing the addition of CDK4/6 inhibitors to adjuvant therapy for eligible HR+/HER2- early breast cancer patients." (PMID 40002156, 2025). "Recently, various clinical trials have discussed the efficacy and safety of CDK4/6 inhibitors in patients with breast cancer, especially in HR(+)/HER2(−) breast cancer." (PMID 40922517, 2025).
breast cancer (continued). "Several biomarkers have been proposed in breast cancers, where the field is more advanced, and include up-regulations of the inhibited kinases CDK4 and CDK6 and their partner cyclin D as well as the main target of phosphorylation, RB." (PMID 40699853, 2025). "In summary, the data reflect how difficult it is to define the exact role of CDK4/6 inhibitors in early-stage breast cancer treatment." (PMID 41228331, 2025). "In early-stage estrogen receptor-positive (ER + ) breast cancer, resistance to endocrine therapy (ET) and CDK4/6 inhibitors (CDK4/6i) often involve a shift away from estrogen-driven proliferation." (PMID 40341770, 2025). "Among these, the application of cell cycle inhibitors, such as CDK4/6 inhibitors, in breast cancer treatment has provided valuable insights." (PMID 40708936, 2025). "The study included 79 adult female patients with advanced breast cancer, who experienced a total of 125 dermatologic adverse events during CDK4/6 inhibitor treatment across eleven centers." (PMID 40422590, 2025). "Together, these observations raise a fundamental question: are all ER+ breast cancers intrinsically resistant to CDK4/6 inhibition or does a subset of patients derive the greatest benefit?" (PMID 41226361, 2025). "Despite significantly improved outcomes in patients with HR+/HER2− breast cancer after treatment with CDK4/6 inhibitors combined with endocrine therapy, drug resistance remains a major therapeutic obstacle." (PMID 40940685, 2025). "In this study, we observed lysosomal changes as a prominent phenotype induced by CDK4/6i in different breast cancer cell types and evaluated the potential therapeutic effect of exposing CDK4/6i-treated breast cancer cells to lysosomotropic agents." (PMID 39930269, 2025). "The clinical success of CDK4/6 inhibitors in breast cancer further validates this kinase as a high-value therapeutic target." (PMID 41471388, 2025). "In conclusion, this meta-analysis examined the role of CDK4/6 inhibitors combined with endocrine therapy in the adjuvant treatment of HR+/HER2− early breast cancer." (PMID 41228331, 2025). "Here, we report that NSRP1, a regulator of alternative mRNA splicing is downregulated in CDK4/6i resistant breast cancer cells and contributes to CDK4/6i resistance by mediating alternative splicing of NSD2 mRNA and activation of the IFN signaling pathway." (PMID 39667501, 2025). "CDK4/6 inhibitors have changed the treatment paradigm for HR+/HER-2- advanced breast cancer, not only by extending the duration of endocrine therapy but also by delaying the time for patients to receive chemotherapy." (PMID 40919150, 2025). "In cancer therapy, CDK inhibitors have revolutionized treatments, especially in advanced breast cancer, with the use of CDK4/6 inhibitors." (PMID 39800748, 2025). "We hereby presented the first report of ILD and its prognosis in two breast cancer patients treated with a combination of CDK4/6i and radiotherapy." (PMID 41244784, 2025). "Clinical studies have corroborated these findings, revealing significant downregulation of circulating Treg cells in HR+/HER2− breast cancer during CDK4/6 inhibitor treatment." (PMID 39930131, 2025). "Retrospective analyses of CDK4/6i in breast cancers reclassified as HER2-low have yielded mixed outcomes." (PMID 40940886, 2025). "The highest benefit in treatment with CDK4/6 inhibitors was achieved from patients with advanced HR+/HER2- breast cancer, in combination with endocrine therapies." (PMID 39800748, 2025). "Recent research focusing on the effects of CDK4/6 inhibitors on the bone microenvironment in breast cancer has revealed the complex role of these agents in osteoclast activity." (PMID 40005476, 2025). "Resistant breast cancer cells compensate for the cytotoxicity of ribociclib, a CDK4/6 inhibitor, by increasing estradiol production, which drives growth signaling." (PMID 41502952, 2025).
breast cancer (continued). "One study investigating the effects of CDK4/6 inhibitors on the breast cancer bone microenvironment has shown effects on osteoclast differentiation and bone resorption." (PMID 40005476, 2025). "Preclinically, we developed ribociclib, abemaciclib or palbociclib-resistant ER+ breast cancer models and investigated the transcriptomic alterations in the CDK4/6i-resistant setting." (PMID 40764324, 2025). "While there are significant limitations in cross-trial comparisons, especially across diseases, this finding again suggests a lower efficacy of CDK4/6 inhibitors in prostate cancer patients compared with breast cancer patients." (PMID 40075623, 2025). "Several early-phase trials are now exploring combination therapy with CDK4/6 inhibitors and immune checkpoint blockade in HR+ breast cancer." (PMID 40566067, 2025). "Overexpression of cyclin D is observed in 50–60% of breast cancer cases, indicating CDK4/6 overactivation." (PMID 39930131, 2025). "As to QoL, adding CDK4/6 inhibitors to endocrine therapy generally preserves health-related quality of life (HR-QoL) in patients with breast cancer and even shows a trend toward pain improvement." (PMID 39860516, 2025). "Palbociclib, ribociclib, and abemaciclib are the three FDA-approved CDK4/6is for breast cancer, which are currently the first- and second-line systemic treatment choices for HR+/human epidermal growth factor-2 negetive (HER2-) advanced/metastatic BC." (PMID 40134916, 2025). "In conclusion, our study provides mechanistic rationale for maintaining CDK4/6i together with ET after disease progression in HR+/HER2− breast cancers that retain an intact Rb/E2F pathway." (PMID 39605351, 2025). "Cyclin-dependent kinase 4/6 (CDK4/6) inhibitors have transformed the management of hormone receptor–positive/HER2–negative (HR+/HER2–) advanced breast cancer, yet evidence for elderly or poor-performance patients remains limited." (PMID 41502524, 2025). "Further, Cyclin D dysregulation further complicates resistance, with CCND1 amplification occurring in ∼50% of breast cancers and enabling persistent CDK4/6-Rb signaling despite inhibitor exposure." (PMID 40421216, 2025). "EMT transcription factors such as SNAIL and ZEB2 can inhibit cell cycle transition by inhibiting the transcription of CCND2 and CCND1, respectively, ZEB1 protein degradation induced by CDK4/6 inhibition blocks breast cancer metastasis." (PMID 39949984, 2025). "The phase III SONIA trial (NCT03425838) directly addressed this issue by comparing early (first-line) versus delayed (second-line) use of CDK4/6 inhibitors in patients with HR+/HER2− advanced breast cancer." (PMID 41383485, 2025). "Abemaciclib, the newest benzimidazole–pyrimidine hybrid CDK4/6 inhibitor for the treatment of certain types of breast cancer, approved in 2017, is the drug that demonstrates the efficacy of the presence of the two heterocyclic rings in its structure." (PMID 40872614, 2025). "We integrated genome-wide association study data with single-cell transcriptomic profiles from ER+ breast cancer patients, focusing on differences between resistant and sensitive responses to CDK4/6 inhibitors." (PMID 40303916, 2025). "Recent studies have revealed the importance of cycle-independent kinase 4 and 6 (CDK4/6) inhibitors in endocrine-resistant breast cancer." (PMID 41458615, 2025). "Abemaciclib, a drug approved for treating HR+/HER2− advanced breast cancer through CDK4/6 inhibition, significantly reduced the fluorescence intensity of GFP‐YAP1." (PMID 39968498, 2025). "The primary mechanism for targeting CDK4/6 in HR+/HER2− advanced breast cancer involves inhibiting RB phosphorylation, resulting in cell cycle arrest." (PMID 39968498, 2025). "Oral selective cyclin-dependent kinase 4/6 inhibitors (CDK4/6is) are currently part of the first-line treatment for metastatic luminal-like breast cancer." (PMID 40361493, 2025).
breast cancer (continued). "Following the approval of abemaciclib and ribociclib for early-stage HR+/HER2- breast cancer, CDK4/6 inhibitors have become integral to adjuvant therapy." (PMID 40002156, 2025). "To explore the RNA-binding proteins (RBPs) involved in the development of CDK4/6i resistance, we analyzed microarray data of ER + breast cancer tissues from patients with palbociclib plus anastrozole (an endocrine therapy drug) treatment (NeoPalAna)." (PMID 39667501, 2025). "The established benefit observed in early breast cancer prompted the investigation of CDK4/6 inhibitors in a boarder population." (PMID 40717978, 2025). "Abemaciclib hindered MCF-7 and MDA-MB-231 breast cancer cell growth and enhanced RT by inducing cell cycle arrest through the inhibition of CDK4 and CDK6 expression and increasing apoptosis." (PMID 40035822, 2025). "Cyclin-Dependent Kinase 4 and 6 (CDK4/6) inhibitors combined with endocrine therapy are effective for ER+/HER2−metastatic breast cancer, yielding markedly higher response rates compared to endocrine therapy alone." (PMID 41373619, 2025). "Endocrine therapy combined with CDK4/6 inhibitors remains a standard treatment for ER+ breast cancer, yet resistance is a prevalent challenge." (PMID 40303916, 2025). "For instance, PI3K inhibitors decrease Cyclin D1 expression, restoring sensitivity of breast cancer cells to CDK4/6 inhibitors." (PMID 41271634, 2025). "Due to the success of CDK4/6 inhibitors in HR+/HER2- breast cancer therapy, their efficacy in other breast cancer subtypes is being tested." (PMID 39800748, 2025). "A growing body of evidence has sought to compare the efficacy and safety of CDK4/6 inhibitors in the management of HR+/HER2− advanced breast cancer." (PMID 39851968, 2025). "Abemaciclib + fulvestrant is currently under clinical investigation in patients with HR+, HER2− breast cancer and progression on prior CDK4/6i + ET (NCT05169567, postMONARCH)." (PMID 40141282, 2025). "A total of 16 studies involving 6,722 patients with advanced breast cancer were included to analyze the toxicity risks of CDK4/6 inhibitor combination therapies." (PMID 41458615, 2025). "The new frontier in the treatment of HR+ HER2− breast cancer is represented by the integration of CDK4/6 inhibitors in the adjuvant setting." (PMID 40277749, 2025). "Patients diagnosed with HR + /HER2-ABC who were treated with CDK4/6i in clinical routine between November 2016 and December 2020 at four certified German Breast Cancer Centers were retrospectively identified." (PMID 39373732, 2025). "As a result, the role of CDK4/6i has expanded from the treatment of advanced breast cancer to early-stage disease and is increasingly being used in curative treatment settings." (PMID 40430137, 2025). "In line with our findings, another recent study found that TEX19 promoted the progression of breast cancer by modulating SKP2-mediated ubiquitination of CDK4." (PMID 41233852, 2025). "Cyclin-dependent kinase 4 and 6 (CDK4/6) inhibitors have significantly improved the treatment of hormone receptor (HR)-positive breast cancer, while immune checkpoint inhibitors have reshaped therapeutic approaches for triple-negative breast cancer." (PMID 41357608, 2025). "By integrating mechanistic insights with clinical evidence, this analysis aims to provide actionable strategies for overcoming therapeutic resistance and maximizing the clinical potential of CDK4/6 inhibitors in breast cancer management." (PMID 40421216, 2025). "Approximately 70% of patients have ER-positive, HER2-negative breast cancer, and the combination of endocrine therapy and a cyclin-dependent kinase 4 and 6 (CDK4/6) inhibitor is one of the standard treatments for this subtype." (PMID 40897668, 2025). "Through this case, we aim to contribute clinical insights into the safety of combining RT with CDK4/6i in early-stage breast cancer." (PMID 40430137, 2025).